ABHD2 (abhydrolase domain containing 2, acylglycerol lipase)
Description:
Progesterone-dependent acylglycerol lipase that catalyzes hydrolysis of endocannabinoid arachidonoylglycerol (AG) from cell membrane. Acts as a progesterone receptor: progesterone-binding activates the acylglycerol lipase activity, mediating degradation of 1-arachidonoylglycerol (1AG) and 2-arachidonoylglycerol (2AG) to glycerol and arachidonic acid (AA). Also displays an ester hydrolase activity against acetyl ester, butanoate ester and hexadecanoate ester. Plays a key role in sperm capacitation in response to progesterone by mediating degradation of 2AG, an inhibitor of the sperm calcium channel CatSper, leading to calcium influx via CatSper and sperm activation. May also play a role in smooth muscle cells migration (By similarity).
Synonyms: LABH2; HS1-2; PHPS1-2
Tractability: Antibody: UniProt places it where antibodies can reach, with high confidence; UniProt predicts a signal peptide or a membrane-spanning region; its Gene Ontology location is reachable by antibodies, with medium confidence. PROTAC: ubiquitination databases record sites on it.
Gene: Protein-coding gene on chromosome 15 (89,087,459 to 89,202,355, forward strand). Ensembl gene ENSG00000140526.
Subcellular location: Cell projection, cilium, flagellum membrane; Cell membrane
Subcellular location (Human Protein Atlas): Cytosol; Flagellar centriole; Connecting piece; Nucleoplasm
Gene Ontology:
Molecular function: acetylesterase activity; diacylglycerol lipase activity; hormone binding; monoacylglycerol lipase activity; nuclear steroid receptor activity; triacylglycerol lipase activity; carboxylesterase activity
Biological process: acylglycerol catabolic process; response to progesterone; sperm capacitation; steroid hormone receptor signaling pathway; medium-chain fatty acid biosynthetic process; medium-chain fatty acid catabolic process; acrosome reaction; nuclear receptor-mediated steroid hormone signaling pathway
Cellular component: sperm flagellum; sperm plasma membrane; acrosomal vesicle; plasma membrane
Genetic constraint (gnomAD): Loss-of-function variants: 20 observed, 50.96 expected, observed/expected ratio (o/e) 0.39, 90% interval 0.28 to 0.57. The upper end of that interval is the gene's LOEUF score, 0.57, which puts it in group 2 of 6, group 1 being the genes least tolerant of losing a copy. Missense variants: 405 observed, 579.96 expected, observed/expected ratio (o/e) 0.7, 90% interval 0.64 to 0.76. Synonymous variants: 209 observed, 225.37 expected, observed/expected ratio (o/e) 0.93, 90% interval 0.83 to 1.04.
Homologues: Orthologues: chimpanzee ABHD2 (99% identical), macaque ABHD2 (99% identical), dog ABHD2 (99% identical), pig ABHD2 (99% identical), mouse Abhd2 (99% identical), rat Abhd2 (99% identical), guinea pig ABHD2 (98% identical), rabbit ABHD2 (98% identical), tropical clawed frog abhd2 (82% identical), zebrafish abhd2a (76% identical), zebrafish abhd2b (75% identical), Drosophila melanogaster Hydr2 (40% identical). Paralogues in human: ABHD3 (23% identical), ABHD1 (21% identical), ABHD15 (18% identical).